CD44 (CD44 molecule (IN blood group))
Diseases named in the same sentence as CD44 in open-access papers (continued):
Sharing a sentence is not in itself a finding about the gene and the disease.
cancer (continued). "Therefore, targeting CD44 could represent a potential therapeutic strategy to overcome drug resistance for cancer cells overexpressing both CD44 and ABCB1." (PMID 36694209, 2023). "Furthermore, TCF3 was correlated with the expression of cancer stemness markers CD44 and CD133." (PMID 37607071, 2023). "Hence, the mere presence of CD44 is insufficient to detect cancer stem cells." (PMID 37108193, 2023). "Therefore, we hypothesized that macrophages promoted the acquisition of cancer stem-like properties leading to GR in PAAD via the Sp1/CD44 axis." (PMID 37553567, 2023). "Moreover, CD44 was down-regulated during the advanced cancer clinical stage in BRCA, and SKCM." (PMID 37117249, 2023). "Collectively, these results infer that CD44 may mediate the immune response in these cancer types." (PMID 37117249, 2023). "Using genetic perturbation and pharmacological inhibition, we aim to probe how interactions likely with CD44 may also potentiate adhesion of cancer cells on senescent peritoneal environments, after verifying if such interactions are crucial for the induction of senescence." (PMID 38043093, 2023). "In addition, the pseudotime analysis indicated that such a cell subset could be a primitive cancer stem cell as evidenced by the relatively high expression of the cancer stem cell biomarker CD44." (PMID 37153569, 2023). "Additionally, the results demonstrated that PDA/HA/Gd3+ could better target the CD44+-expressing cancer cells than PDA/Gd3+." (PMID 36934115, 2023). "Accordingly, targeting CD44 upstream regulators may provide a new option for cancer therapy." (PMID 37000153, 2023). "In addition, its interaction with surface cell receptors EGFR, human epidermal growth factor receptor 2(HER-2) and CD44 in malignant epithelial cells may be responsible for proliferation and cellular motility in early stages of cancer." (PMID 37259101, 2023). "The multifaceted involvement of CD44 in various pathological activities within cancer cells necessitates comprehensive investigation into its biological function, thereby facilitating the development of novel therapeutic approaches for patients afflicted with high-CD44 tumors." (PMID 37509716, 2023). "CD44 is a multi-functional receptor molecule with important roles not only in mediating cell-to-cell and cell-to-extracellular matrix interactions, but also in transducing intracellular signaling pathways that promote cell migration, invasion, proliferation, and tumorigenesis in malignant tumors." (PMID 37760811, 2023). "Cluster of differentiation 44 (CD44) is a cell surface transmembrane glycoprotein that is expressed in various human cell types and has been extensively studied in relation to its involvement in physiological processes, as well as its significant roles in tumorigenesis and cancer metastasis." (PMID 37509716, 2023). "Furthermore, CD44 lowers the vulnerability of cancer cells to oxidative stress and ferroptosis." (PMID 36875702, 2023). "Therefore, targeted modulation of CD44/HA correlated to cancer growth inhibition could be explored as a novel direction in antitumor therapy." (PMID 37107200, 2023). "Therefore, we tentatively proposed that CD44 may promote malignant phenotypes of cancer cells, which could thus be used as a potential therapeutic target for some specific cancer types." (PMID 37117249, 2023). "In addition, CD133, CD44, and Nanog may have clinical roles in predicting pathological stages, cancer recurrence, and therapy resistance in CRC." (PMID 37762705, 2023). "Besides, the expression of CD44 was significantly associated with TMB and MSI in 10 types and 6 types of cancer, respectively, indicating it could be exploited as a potential biomarker predicting immunotherapy outcomes." (PMID 37117249, 2023). "Hence, targeting CD44 as a cancer therapeutic target requires careful evaluation." (PMID 36936902, 2023).
cancer (continued). "Consequently, the dissociation of CD44 and HA caused by CAP-generated RONS could be a crucial mechanism for cancer treatment based on oxidative stress." (PMID 37759771, 2023). "The analysis of trajectories highlighted the stability of the modeled HABD and TMD, as well as the conformational flexibility and structural dynamics of the unstructured regions that may allow CD44 to perform its unconventional activity, as has been observed in cancer and immune response." (PMID 37509083, 2023). "Additionally, the disruption of specific HA and CD44 isoforms linkage could have a therapeutic effect on cancer." (PMID 37107200, 2023). "CD44 is ubiquitously found on the cell surface of mesenchymal, endothelial, and epithelial cells and it controls cellular behavior, such as homing of leukocytes, adhesion of fibroblasts to extracellular matrix, and cancer cell invasion and adhesion to endothelium." (PMID 36831425, 2023). "Notably, the functional role of CD44 on cancer development and progression has become a research hotspot and will assist in understanding its potential role as a prognostic biomarker for cancers." (PMID 37117249, 2023). "The transmembrane glycoprotein CD44 has been recognized as a characteristic CSC surface marker that may be used independently or in combination with other markers for the identification of CSCs in various cancers." (PMID 36902135, 2023). "Overall, the literature presented here supports the role of the hyaluronan/CD44 axis in the acquisition of a migratory, metastatic, and chemotherapy-resistant phenotype, while also highlighting the crucial role of the microenvironment in enabling the cancer-promoting function of CD44." (PMID 37958796, 2023). "Furthermore, DRC/SA nanoparticles were coated with hyaluronic acid to shield their cationic toxicity and enhance intracellular saporin delivery efficiency via the recognition of CD44 overexpression on the cancer cell membrane, which induced the death of various cancer cell lines." (PMID 37367265, 2023). "It was also shown that aberrant PD-L1 expression on the CD133+CD44+ CSC cell population was associated with increased activation of the Notch3/mTOR signalling axis and HMGA1-dependent pathways, including PI3K/AKT and MEK/ERK pathways in cancer cells in vitro and in vivo." (PMID 36980527, 2023). "CD147 is an immunoglobulin-like receptor that is highly expressed in various cancers and involved in the growth, metastasis, and activation of inflammatory pathways via interactions with various functional molecules, such as integrins, CD44, and monocarboxylate transporters." (PMID 36385956, 2022). "Therefore, CD44 is a promising target for cancer diagnosis and therapy." (PMID 35628345, 2022). "The results showed that most genes were abnormally expressed in most of the tumors when compared to normal tissues, such as CD44 expression which is higher in most cancers than normal tissues, indicating that CD44 may play an important role in the development of tumors." (PMID 35955933, 2022). "However, there are opposite views on the role of CD44 in cancer." (PMID 36232605, 2022). "CD44 has been shown to play an important role in the signalling of pancreatic and gastric cancer stem cells and is also an important marker for these cancers, because it is highly expressed in many cancers, and it is involved in the regulation of cancer metastasis." (PMID 34939255, 2022). "However, the tendency of GFP+ cancer cells closing to blood vessels induced by THP-1-derived M2-like macrophages was significantly reduced in MCF7/sh-CD44 tumors, suggesting that the knockdown of CD44 attenuated the collective detachment induced by TAMs in vivo." (PMID 35680853, 2022). "Therefore, the T-b, T-f, A-b, A-b, and UB-010 fractions could be considered capable of reducing the expression of CD44, impacting the differentiation and contributing to diminishing cancer progression and metastasis." (PMID 35631686, 2022).
cancer (continued). "CD44, a non-kinase transmembrane glycoprotein, widely expressed on cell membranes, is implicated in many physiological and pathological processes, which include development, inflammation, immune responses, wound healing, and cancer progression." (PMID 35024436, 2022). "Furthermore, its correlation with the expression of CD44 indicates a role in cancer stemness." (PMID 35054968, 2022). "Therefore, high CD44 expression is correlated with poor prognosis in cancer treatment." (PMID 36293491, 2022). "Moreover, when CD44 binds to HA, it plays a pivotal role in cancer invasiveness." (PMID 35464064, 2022). "CD44 protein is overexpressed on the cell surface of cancer stem cells in GC tissues, and binding of hyaluronan to CD44 has been reported to affect various downstream signaling pathways, leading to cancer invasion, metastasis, and resistance to chemoradiotherapy." (PMID 35595817, 2022). "Therefore, CD44 is thought to be a promising target for cancer diagnosis and therapy." (PMID 35628345, 2022). "In addition, the predominant co-expression of GPNMB in myeloid cells and CD44 in cancer cells in chemo-resistant samples may provide us with the mechanism underlying chemo-resistance." (PMID 36248860, 2022). "It has also been observed that CAFs derived from wild-type mice express high levels of CD44 in hypoxic and low-nutrition environments, which could maintain the stemness of cancer stem cells, while CD44-deficient CAFs do not have these properties." (PMID 35681617, 2022). "CD44 has been tightly linked to EMT, as it is upregulated by TGFβ, is directly involved with STAT3, β-catenin, and AKT signaling, and promotes tumor invasion and metastasis by contributing to the adhesion of cancer cells to the endothelium and fibronectin-enriched matrices." (PMID 36358747, 2022). "Moreover, a codelivery vector including CS loaded with small interfering RNA and paclitaxel has been proven to have a mighty targeting effect towards CD44-overexpressing cancer cells." (PMID 36432183, 2022). "In addition, knockdown of CMTM2 could antagonize the effects of SJZ on SGC7901 cells' expression of SOX2, NANOG, and CD44 and their cancer stem cell-like properties." (PMID 35873650, 2022). "Indeed, limma analysis of differentially expressed genes indicated an increased expression of four genes related to cancer stemness: the pluripotency factor KLF4, the PLAUR gene encoding for the urokinase plasminogen activator surface receptor (uPAR), CD44 and CD166." (PMID 36077264, 2022). "Thus, the correlation between glutamine uptake and CD44 may be related to the function of xCT, and in some cancers, glutamine addiction is explained by the functional coupling of xCT and ASCT218." (PMID 35365739, 2022). "Furthermore, it has been reported that the accumulation of excess ROS in tumor cells inhibits cancer progression by arresting cancer growth and inducing cell death, while CD44-mediated suppression of intracellular ROS has been shown to result in resistance to cancer therapy." (PMID 35330413, 2022). "Later, we demonstrated that cells significantly enriched for CD44s displayed CD44-mediated invasion in vitro, reinforcing the close link between this isoform and disease progression and its potential for targeting more aggressive subpopulations of cancer cells." (PMID 35547758, 2022). "In addition, CD44, an adhesion receptor expressed on the surface of many cancer cells that mediates cell–cell interactions and cell migration, has been recognized for its multifunctional roles in survival, angiogenesis, metastasis and activation of immune responses and inflammation." (PMID 35760832, 2022). "Furthermore, CD44v formation was regulated by splicing factors, serine/arginine-rich splicing factor (SRSF)-1 and -3, instead of ESPR1, which is well known to induce a splicing switch from the CD44 standard form to CD44v, particularly to CD44v8–10 in cancer cells." (PMID 35130955, 2022).
cancer (continued). "In addition, the protein and mRNA expression levels of USP6NL, pluripotency and cancer stem cell markers (CD44 and CD133), transcription factor (Nanog and SOX2), and efflux transporter ABCG2 were significantly overexpressed in the U87MG-R and T98G-R sphere compared with the parental control." (PMID 35884836, 2022). "Targeting CD44 may be a promising therapeutic strategy for cancer management." (PMID 34774101, 2021). "The activated ERK signaling could directly or indirectly modulate cell cycle-related proteins, such as CDKs and cyclins controlling G1–S transition phase and pro-metastatic factors, such as EMT markers and MMPs, as well as some cancer stem cell-related genes, such as CD44 and NANOG19–23." (PMID 34035231, 2021). "Interestingly, CD44 generated in HEK293 cells, which were cloned from human embryonic kidney, was glycosylated in the mAb target region of CD44, indicating that cancer cells leave this region unglycosylated and possibly, this provides a unique cancer cell target." (PMID 33891595, 2021). "Likewise, the overexpression of CD44 confers aggressive and distant metastasis in cancer cells." (PMID 34588926, 2021). "We then ask whether the binding affinity of CD44 and HA was different in both cancer cells." (PMID 34770956, 2021). "CD44 (cluster determinant 44), which is considered the main cell surface receptor for HA, is overexpressed in many cancers, thus HA may be used for targeted delivery of anti-cancer drugs." (PMID 35009380, 2021). "Hence, CD44 positive cells might contribute to the damaged cells that enter the carcinogenesis process and enable cancer cells to resist anti-cancer treatment via regulating redox status." (PMID 33780455, 2021). "It is known that the CD44 antigen is a multi-structural and multi-functional cell-surface glycoprotein involved in cell-to-cell interaction, cell adhesion, cell proliferation and differentiation, migration, and other biological aspects, and it has also been found in cancer cells." (PMID 34830890, 2021). "Consequently, the HA-based drug delivery system could realize CD44-targeting as well as hyaluronidase-responsive drug delivery for different cancers." (PMID 34336811, 2021). "Thus, our qualitative and quantitative data revealed that the DDM system is specifically and selectively bound to the overexpressed FR- and CD44 receptors in cancer cells via CD44/FR- receptor-mediated endocytosis and the responsive release under acidic conditions." (PMID 34771733, 2021). "While we and others have shown that CD44 regulates MDR1 expression in various cancers and controls COX2-PGE2 signaling in CRC, whether YB-1 may be linked to the ability of CD44v6 to induce the expression of genes linked to stemness and drug resistance in CD44v6+CICs is not known." (PMID 33451103, 2021). "More importantly, we also explored the cell stemness of six-FBXOs in PDAC by using the GSE51971 dataset, whose data were classified into triple-positive group and triple-negative group according to whether these expressed the three important cancer stem cell markers, CD44, CD133, and EpCAM." (PMID 35046938, 2021). "Moreover, in many cancers of epithelial origin, the up-regulation of CD44 has been observed." (PMID 34073987, 2021). "However, during cancer progression, CD44 expression increased in HCC progenitor cells (HcPCs)." (PMID 31991677, 2020). "Circulating cancer cells rolling over the vascular walls are regulated by the engagement of endothelial cell-expressed E-selectin and P-selectin with tumor cell surface-expressed glycol proteins such as CD44, CD24, sulfate-glycosaminoglycans (CS-GAGs), and sialylated glycosphingolipids." (PMID 33379338, 2020). "It remains to be further investigated whether the ECM SRGN derived from H460 cells may help in recruiting growth factors and ligands through CS-E-enriched GAG chains and regulate pro- or anti-tumorigenic signaling, such as WNT/β-catenin pathway, by CD44 platform in cancer progression." (PMID 31898491, 2020).
cancer (continued). "Furthermore, in several cancer models, CD44 is highly expressed on cancer stem cells." (PMID 32636398, 2020). "In addition, CD44 can serve as an adverse prognostic marker among cancer population." (PMID 33303029, 2020). "Furthermore, thereis a significant relationship between the CD44 rs187115 andliver cancer." (PMID 31376327, 2020). "In addition, there are several overexpressed HA binding receptors in cancer cells compared to normal cells, such as cluster of differentiation 44 (CD44), lymphatic vessel endocytic receptor (LYVE-1), and the receptor for hyaluronic acid-mediated motility (RHAMM)." (PMID 32290285, 2020). "Evidences show that the other CD44 SNPs could alsocontribute to cancer." (PMID 31376327, 2020). "Furthermore, CD44 expressed by CAFs may interact with CRC cells to support cancer cell survival in hypovascular areas but it needs further investigations." (PMID 32984031, 2020). "Therefore, understanding the down-stream targets of the CD44–hyaluronan interaction could also have implications for cancer biology." (PMID 31996681, 2020). "CD44 was in fact hypothesized to be a marker of GBM cancer stem cells." (PMID 33374813, 2020). "As CD44 is widely accepted as one of the most reliable cancer stem cell markers in various kinds of cancer, and because BSH-polyR directly binds to the CD44 cell-surface protein we thought that BSH-polyR could be a promising cancer stem cell-directed 10B agent." (PMID 32977522, 2020). "Previous studies have shown that miRNAs could regulate cancer development by targeting CD44." (PMID 31892992, 2020). "Thus, nanomedicine targeting CD44 in GBM to deliver anti‐PLD1 drugs or natural anti‐cancer molecules in combination with TMZ could offer a new therapeutic opportunity for GBM target therapy." (PMID 32725633, 2020). "Additionally, HA has recently been proposed to detect CD44 in the diagnosis of specific tumors and recently targeted molecular imaging with HA as specific magnetic resonance contrast agents have been suggested for the diagnosis and treatment of CD44-overexpressing cancer." (PMID 32708202, 2020). "CD44, as the receptor for hyaluronic acid (HA), mediates intracellular cell signaling through its interaction with cytoskeletal proteins and is involved in cell adhesion, migration, drug resistance, and signal transmission in some drug-resistant cancer cell lines." (PMID 32760666, 2020). "Except CD44+CD133+ subset and OV6+ subset, we found that HBx upregulated a subset with positive expression of ABCG2, a drug resistance-associated protein, which had been characterized by high expression of cancer stemness-related proteins, including Oct4, Bmi-1, and CD44." (PMID 32168902, 2020). "Thus, despite the naturally poor immunogenicity of MOC2-luc cells, CD44-targeted NIR-PIT could elicit host anti-cancer immunity in these “cold” tumors." (PMID 33322807, 2020). "Despite its development to treat a number of cancer indications being halted in 2015, recently, foretinib was shown to be able to inhibit cancer cell stemness and diminish the proliferative ability in some gastric cancers by counteracting CD44 and cMet tyrosine kinases." (PMID 33297561, 2020). "We observed enrichment of human embryonic stem cell pluripotency genes along with transcriptional regulation of pluripotent stem cells that might lead to activation of POU5F1 (OCT4), SOX2, CD44, NANOG, and other genes associated with self-renewal and drug resistance of cancer cells." (PMID 33339129, 2020). "Of note, the CD44 molecule is described to strongly interact with hyaluronan, a major component of the extracellular matrix and which plays a pivotal role in inflammation and cancer as well as in locomotion and B cell migration on stromal cells and reticular fibers." (PMID 33028033, 2020). "Furthermore, the populations of cancer stem cells (CSCs), known to be important for cancer resistance and recurrence, present in the spheroid models were also evaluated using two different markers (CD44 and CD117)." (PMID 33335914, 2020).